SLC7A5 (solute carrier family 7 member 5)
Diseases named in the same sentence as SLC7A5 in open-access papers (continued):
Sharing a sentence is not in itself a finding about the gene and the disease.
epilepsy (5 papers, 2018 to 2021). A brain disorder characterized by episodes of abnormally increased neuronal discharge resulting in transient episodes of sensory or motor neurological dysfunction, or psychic dysfunction. "The silencing effect of Slc7a5 may be noteworthy in the context of an apparent paradox in the characterization of epilepsy-associated Kv1.2 mutations." (PMID 30356053, 2018). "Taken together, our data and previous reports raise the possibility that central glutamine deficiency may upregulate slc1a5 and Slc7a5 gene expression, activate the mTOR pathway, and contribute to astrogliosis and epilepsy, some of the key features of experimental SSADHD." (PMID 33204597, 2020). "In addition, epilepsy-linked gain-of-function Kv1.2 mutants exhibit enhanced sensitivity to Slc7a5." (PMID 30356053, 2018). "Although not reported in the few SLC7A5 patients published to date, this suggests that patients may be susceptible to light-flashing-induced seizures, as is the case with certain types of epilepsy in humans." (PMID 33330465, 2020).
glioblastoma (5 papers, 2020 to 2022). The most malignant astrocytic tumor (WHO grade IV). "Increased SLC7A5 expression has been reported in many cancer types including triple-negative breast cancer, colon cancer, lung cancer, glioblastoma, and prostate cancer." (PMID 35163079, 2022). "C-Myc and n-Myc control of SLC7A5 expression has been demonstrated in glioblastoma and neuroblastoma, respectively." (PMID 35163079, 2022). "The TCGA glioblastoma dataset was analysed for the expression of TSPO and SLC7A5 (=LAT1), encoding for the molecular targets of TSPO- and FET-PET, and for AIF1, as we found a high TSPO level in microglia and macrophages." (PMID 31963507, 2020). "However, glioblastoma cells not only induce SLC7A5 in response to hypoxia through HIF2α but also, the HIF1α isoform is involved in its expression." (PMID 33321829, 2020).
liver cancer (5 papers, 2019 to 2026). An epithelial or non-epithelial malignant neoplasm that arises from the liver. "In line with the elevated expression of SLC1A5 and SLC7A5 in liver cancer, Trp levels were elevated in livers of mice upon MYC upregulation, as measured by tandem mass spectrometry (LC-MS/MS)." (PMID 38769298, 2024). "Using RNA-seq from the TCGA data set for liver cancer, we found that about 40% of patients with HCC had elevated SLC7A5, 50% had elevated SLC1A5 and 64% had either or both elevated." (PMID 38769298, 2024). "Our analysis revealed HCSC important hubs as candidate regulators for targeting hepatic cancer stemness such as, miR-148a, miR-214, E2F family, MYC and SLC7A5." (PMID 30944375, 2019).
non-small cell lung carcinoma (5 papers, 2019 to 2025). A group of at least three distinct histological types of lung cancer, including non-small cell squamous cell carcinoma, adenocarcinoma, and large cell carcinoma. "Altered regulation of SLC7A5 has been observed in various cancer types, including ovarian and non-small-cell lung cancers." (PMID 40535120, 2025). "As demonstrated in the extant literature, METTL3 in CAFs-derived exosomes has been shown to promote proliferation, invasion, and glutamine metabolism in non-small cell lung cancer (NSCLC) cells by inducing m6A modification of SLC7A5 and stabilising its expression." (PMID 40598593, 2025).
rheumatoid arthritis (5 papers, 2018 to 2025). A chronic, systemic autoimmune disorder characterized by inflammation in the synovial membranes and articular surfaces. "In the progression of rheumatoid arthritis, pronounced upregulation of SLC7A5 has been observed in monocytes and is negatively correlated with the prognosis." (PMID 39161963, 2024). "Moreover, increased expression of SLC7A5 by peripheral monocytes from rheumatoid arthritis (RA) patients positively correlates with clinical parameters, such as CRP and ESR, suggesting that the SLC7A5-mediated AA influx is related to inflammatory conditions." (PMID 29422900, 2018). "Moreover, expression of SLC7A5 is significantly elevated in monocytes derived from patients with rheumatoid arthritis (RA), a chronic inflammatory disease, and was also markedly induced by LPS stimulation of both monocytes and macrophages from healthy individuals." (PMID 29422900, 2018). "SLC7A5, as an amino acid transporter, participates in cell invasion and regulates the protein levels of MMP3 and MMP13 through mTOR signaling in rheumatoid arthritis fibroblast-like synovial cells." (PMID 35785145, 2022).
biliary tract cancer (4 papers, 2013 to 2025). "An example of the therapeutic use of targeting AATs is exemplified by JPH203 (nanvuranlat), an inhibitor of the large amino acid transporter LAT1 (SLC7A5), which is currently in clinical trials for the treatment of biliary tract cancer." (PMID 40775108, 2025). "JPH203, a novel and selective SLC7A5 inhibitor, is currently being evaluated in a phase 2 clinical trial in patients with advanced biliary tract cancers (UMIN Clinical Trials Registry UMIN000034080) based on the promising results of the phase 1 clinical trial in patients with advanced solid tumors." (PMID 31803607, 2019). "JPH203, an SLC7A5 (LAT1) inhibitor, which is also highly expressed in HNSCC, has completed phase II clinical trials in advanced biliary tract cancer and has shown promise in the prevention of biliary tract cancer." (PMID 40362545, 2025).
bladder cancer (4 papers, 2015 to 2024). "SLC7A5 was associated with adverse prognosis in bladder cancer patients, activating the Wnt pathway and promoting bladder cancer cell cycle progression, proliferation, migration, and invasion." (PMID 38790003, 2024). "EGFR-targeted therapy, cancer immunotherapy, and radiation therapy were effective for patients with high SLC7A5 expression in bladder cancer." (PMID 38790003, 2024). "This contradicts our results, as our study showed that high expression of SLC7A5 in bladder cancer promotes the infiltration and cytotoxic function of CD8 + T cells in vitro and in vivo, thereby inhibiting tumor growth." (PMID 38790003, 2024). "SLC7A5 can predict therapeutic response to immunotherapy, radiotherapy and chemotherapy in bladder cancer patients." (PMID 38790003, 2024). "Altogether, our data identify METTL3/ALKBH5 and SLC3A2/SLC7A5 as the potential therapeutic targets and pave the way for future development of therapy for bladder cancer related to PAHs." (PMID 38267663, 2024). "We systematically analyzed the correlation between SLC7A5 and bladder cancer through various approaches, including bioinformatics, western blotting, cell cycle analysis, cell proliferation assays, and invasion experiments." (PMID 38790003, 2024). "Consistent with our findings, we found that overexpression of SLC7A5 significantly increased the proliferation, invasion, and migration of bladder cancer cells." (PMID 38790003, 2024). "During the malignant transformation, dysregulation of METTL3/ALKBH5 induced the up-regulation of m6A levels on SLC3A2/SLC7A5 mRNA in cells, which promoted translation and expression of SLC3A2/SLC7A5, and thus accelerated bladder cancer growth and metastasis." (PMID 38267663, 2024). "Coculture of bladder cancer cell lines overexpressing SLC7A5 with human peripheral blood CD8+ T cells revealed that overexpression of SLC7A5 enhances the cytotoxicity of CD8+ T cells." (PMID 38790003, 2024). "Our data suggests that targeting METTL3/ALKBH5 and their downstream genes SLC3A2/SLC7A5 may be a potential therapeutic strategy for bladder cancer." (PMID 38267663, 2024). "Flow cytometry results indicated an increase in the number of cells in the G0/G1 phase and a decrease in the number of cells in the S phase following SLC7A5 knockdown, suggesting that SLC7A5 knockdown induces cell cycle arrest at the G0/G1 phase in bladder cancer cells." (PMID 38790003, 2024). "Therefore, our results indicate that SLC3A2/SLC7A5 exert the enormous function on promoting the malignant progression of bladder cancer cells in vitro and vivo." (PMID 38267663, 2024). "This study aimed to understand the role of SLC7A5 in bladder cancer." (PMID 38790003, 2024). "Taken together, our results revealed that the m6A modification-mediated SLC3A2/SLC7A5 translation promoted 3-MC-induced uroepithelial transformation, suggesting that targeting m6A modification of SLC3A2/SLC7A5 may be a potential therapeutic strategy for bladder cancer related to PAHs." (PMID 38267663, 2024).
cervical cancer (4 papers, 2019 to 2025). A primary or metastatic malignant neoplasm involving the cervix. "For instance, EGLN1 overexpression has been associated with poorer survival in cervical squamous cell carcinoma, and knockdown of SLC7A5 has been shown to significantly suppress the migration and invasion capabilities of cervical cancer cells." (PMID 41431124, 2025).
cholangiocarcinoma (4 papers, 2018 to 2023). A carcinoma that arises from the intrahepatic biliary tree (intrahepatic cholangiocarcinoma) or from the junction, or adjacent to the junction, of the right and left hepatic ducts (hilar cholangiocarcinoma). "A study obtained four genes associated with ferroptosis (SLC2A1, SLC2A6, SLC7A5, ZEB1) by analyzing RNA-seq data after PDT in cholangiocarcinoma." (PMID 37894410, 2023). "PDT can up-regulate the expression of SLC2A1, SLC2A6, and SLC7A5 and inhibit the expression of ZEB1, and four ferroptosis-sensitive genes are associated with the prognosis of patients with cholangiocarcinoma." (PMID 37894410, 2023).
colitis (4 papers, 2025). Inflammation of the colon. "Additionally, in a DSS-induced colitis model, SLC7A5 expression was also significantly increased relative to controls (P < 0.05)." (PMID 40729322, 2025). "Clinically, SLC7A5 is upregulated in IBD, and its blockade ameliorates T cell-driven colitis in vivo." (PMID 41347630, 2025). "Kynurenine has been shown to protect barrier function in a colitis mouse model and, along with tryptophan, crosses the BBB via the amino acid transporter SLC7A5 or L-type amino acid transporter 1, affecting neurotransmitter production." (PMID 41169367, 2025).
neuroblastoma (4 papers, 2020 to 2022). Neuroblastoma (NB) is the most common solid, extracranial childhood tumor. "Knockdown of SLC7A5 or SLC43A1 expression in neuroblastoma cells represses the uptake of essential amino acids, as determined by 3H-Leucine transport assay, leading to a significant decrease in the intracellular levels of isoleucine, leucine, phenylalanine, and valine." (PMID 36077650, 2022). "Moreover, HIF2α controls SLC7A5 expression in other biological settings, such as neuroblastoma cells." (PMID 33321829, 2020). "In response to IL12/15 stimulation, NK cells from neuroblastoma patients significantly upregulated CD98 expression and uptake activity through SLC7A5 in CD56bright cells compared to pediatric controls which unexpectedly, did not upregulate either expression or activity of this nutrient receptor." (PMID 36276144, 2022). "Moreover, SLC7A5 or SLC43A1 depletion reduces MYCN expression by interfering with MYCN mRNA translation and attenuates neuroblastoma cell growth in vitro and in vivo." (PMID 36077650, 2022).
ovarian carcinoma (4 papers, 2015 to 2024). A malignant neoplasm originating from the surface ovarian epithelium. "Upon correlating our study's findings with the existing literature, we observed that silencing FGF8 in ovarian cancer cells resulted in the downregulation of several proteins associated with cancer progression, including SLC7A5, FHL2, SPATS2L, and DAD1." (PMID 39309198, 2024).
clear cell renal cell carcinoma (3 papers, 2018 to 2024). "LAT1(SLC7A5) and LAT2(SLC7A8) serve as primary transporters for BCAAs, exhibiting high expression levels in glioblastoma and clear cell renal cell carcinoma." (PMID 38218942, 2024).
head and neck cancer (3 papers, 2021 to 2025). A primary or metastatic malignant neoplasm affecting the head and neck. "SLC3A2/CD98hc and two L-type amino acid transport binding partners, LAT1 and ascAT1 (derived from SLC7A5 and SLC7A10, respectively), were analyzed independently as prognostic markers in bladder, breast, cervical, lung, renal and head and neck cancers." (PMID 34112739, 2021).
head and neck squamous cell carcinoma (3 papers, 2022 to 2024). A squamous cell carcinoma that arises from any of the following anatomic sites: lip and oral cavity, nasal cavity, paranasal sinuses, pharynx, larynx, and salivary glands. "Studies indicate that inhibiting autophagy-related proteins, specifically SLC7A5/LAT1 and ATG5, increases radiosensitivity in head and neck squamous cell carcinomas (HNSCC)." (PMID 39655194, 2024).
Hyperglycemia (3 papers, 2022 to 2024). An increased concentration of glucose in the blood. "We further observed downregulation of many other amino acid transporters such as Slc1a5 and Slc7a5 by long-term hyperglycemia." (PMID 38742438, 2024).
Hyperphenylalaninemia (3 papers, 2020 to 2025). "In our cellular experiments, carriers of the SLC7A5 variant exhibited hyperphenylalaninemia-related upregulation of the LAT1 transporter, accompanied by a corresponding decrease in transcriptomic activity of both the cellular proteasome complex and the FOXO signalling pathway." (PMID 41387948, 2025). "Future studies on cellular uptake of thyroid hormones in fibroblasts exposed to hyperphenylalaninemia could aim to verify the functional role of the rs113883650 variant of the SLC7A5 gene." (PMID 32874918, 2020). "We recently demonstrated that carriership of a common variant rs113883650 of the LAT1(SLC7A5) gene, encoding the major transmembrane transporter of phenylalanine, may affect the concentration of this amino acid in the brain in teenagers and young adults with severe hyperphenylalaninemia." (PMID 35176108, 2022). "This is because hyperphenylalaninemia competitively blocks the SLC7A5/SLC3A2 complex-mediated transport of thyroid hormones." (PMID 32874918, 2020).
inflammatory bowel disease (3 papers, 2020 to 2025). A spectrum of small and large bowel inflammatory diseases of unknown etiology. "Future investigations into SLC7A5’s involvement in diverse diseases, including inflammatory bowel disease, are poised to yield fresh insights and possibilities for advancing ferroptosis research applications." (PMID 40729322, 2025).
Insulin resistance (3 papers, 2014 to 2025). Increased resistance towards insulin, that is, diminished effectiveness of insulin in reducing blood glucose levels. "Furthermore, research involving human adipose tissue has revealed changes in SLC7 transporter expression, notably of LAT1 (SLC7A5), in individuals affected by obesity and insulin resistance." (PMID 40469683, 2025).
lung adenocarcinoma (3 papers, 2022 to 2024). A carcinoma that arises from the lung and is characterized by the presence of malignant glandular epithelial cells. "Key gene that regulated SLC7A5 in KRAS mutant lung adenocarcinoma was screened by RNA sequencing and bioinformatics analysis." (PMID 36505791, 2022). "Our analysis of TCGA database showed that expression of the tryptophan transporter, solute carrier 7A5 (SLC7A5) is significantly upregulated in lung adenocarcinoma compared with normal controls and positively correlates with expression of glycolytic enzyme GAPDH." (PMID 37095081, 2023). "ZNF24 promoted the growth of KRAS mutant lung adenocarcinoma by upregulating SLC7A5 protein expression, which suggested that ZNF24 is a new biomarker of KRAS mutant tumors and could be a new potential therapeutic target for Ras-driven tumors." (PMID 36505791, 2022). "ZNF24 and SLC7A5 expression were significantly increased in KRAS mutant lung adenocarcinoma." (PMID 36505791, 2022). "We found a novel gene, ZNF24, which upregulated SLC7A5 protein expression rather than mRNA expression in KRAS mutant lung adenocarcinoma." (PMID 36505791, 2022).
lymphoma (3 papers, 2017 to 2023). A malignant (clonal) proliferation of B- lymphocytes or T- lymphocytes which involves the lymph nodes, bone marrow and/or extranodal sites. "In lymphoma cells, rapamycin-induced mTORC1 inhibition reduces the expression of a variety of amino acid transporters, including LAT1 (SLC7A5)." (PMID 33511116, 2020).
Obesity (3 papers, 2020 to 2023). Accumulation of substantial excess body fat. "Together, these results suggest that Slc7a5 deficiency in LepR-expressing neurons exacerbates HFD-induced obesity and metabolic dysfunction." (PMID 36862514, 2023). "In this study, Slc7a5 deficiency led to leptin insensitivity in LepR-expressing neurons and decreased sympathetic outflow prior to the onset of obesity." (PMID 36862514, 2023). "Slc7a5 deficiency caused sympathetic dysfunction and leptin insensitivity in LepR-expressing neurons before obesity onset." (PMID 36862514, 2023). "Mice lacking LAT1 (encoded by solute carrier transporter 7a5, Slc7a5) in LepR-expressing neurons exhibited obesity-related phenotypes and higher bone mass." (PMID 36862514, 2023). "To this end, we selectively reexpressed Slc7a5 in LepR-expressing neurons by stereotaxically and bilaterally microinjecting a Cre-inducible adeno-associated virus (AAV), AAV-hSynI-DIO-Slc7a5-mCherry (AAV-Slc7a5), into the VMH of LepR-Cre Slc7a5fl/fl mice before the onset of obesity." (PMID 36862514, 2023). "Glutamine is essential for CD8 T cell function and a substrate for SLC7A5, suggesting that low levels of glutamine could impair CD8 T cell function in obesity." (PMID 35103755, 2022).
osteoporosis (3 papers, 2021 to 2025). A condition of reduced bone mass, with decreased cortical thickness and a decrease in the number and size of the trabeculae of cancellous bone (but normal chemical composition), resulting in increased fracture incidence. "IL-18 demonstrated a protective effect against osteoporosis in our study, possibly because IL-18 promotes osteogenic differentiation of hBMSCs through the SLC7A5/c-MYC pathway." (PMID 39091505, 2024). "The expression of SLC7A5 in osteoclasts of a mouse osteoporosis model was reportedly significantly reduced." (PMID 34977008, 2021). "It was shown that SLC7A5 knockout mice developed osteoporosis." (PMID 34977008, 2021). "Additionally, research has indicated that slc7a5 knockout mice developed osteoporosis." (PMID 39857294, 2025).
renal cell carcinoma (3 papers, 2019 to 2020). "Therefore, it is also possible that USF2 also participates in the HIF2α-dependent expression of PHD3, OCT-4, NDRG1, TGFA, GLUT1, CCND1 and SLC7A5 in renal cell carcinoma." (PMID 33321829, 2020).
Sepsis (3 papers, 2024 to 2025). Sepsis is defined as life-threatening organ dysfunction caused by a dysregulated host response to infection. "It was also reported that cuproptosis-related genes (POR, SLC7A5, and STAT3) or N6-methyladenosine (m6A) methylation were strongly involved in the pathological process of sepsis-induced cardiomyopathy." (PMID 39427197, 2024). "In addition to these alternative metabolic routes, specific glutamine transporters such as SLC1A5 (ASCT2) and SLC7A5 (LAT1) play crucial roles in glutamine uptake and metabolic reprogramming in both cancer and sepsis." (PMID 40563999, 2025). "The intersection of databases RM2Target, GSE179554-6 h, and GSE179554-12 h presented 7 genes (Mt1, Mt2, Alpl, Angptl4, Apod, Slc7a5, and Timp1) that may bind towards YTHDC1 in sepsis." (PMID 38842666, 2024).
small cell lung carcinoma (3 papers, 2013 to 2024). Small cell lung cancer (SCLC) is a highly aggressive malignant neoplasm, accounting for 10-15% of lung cancer cases, characterized byrapid growth, and early metastasis. "SLC7A5 siRNA significantly reduced proliferation of small cell lung cancer cells and KB human oral cancer cells." (PMID 23527086, 2013).